GSDME (gasdermin E)
Diseases named in the same sentence as GSDME in open-access papers (continued):
Sharing a sentence is not in itself a finding about the gene and the disease.
cancer (continued). "The results showed that dietary polyphenols induced pyroptosis in cancer cells mainly through the GSDMD and GSDME pathways." (PMID 36091247, 2022). "On the other hand, caspase-3 triggers pyroptosis by directly cleaving gasdermin E (GSDME), which has been observed in several cancer cell models with high GSDME expression." (PMID 35997950, 2022). "GSDMC, GSDMD, GSDME, ZBP1, AIM2, DHX9 and NLRP3 demonstrated significant amplification across cancers." (PMID 36605187, 2022). "In summary, the activation of caspase-3/GSDME-dependent pyroptosis by nanostructured toxins targeting CXCR4 opens a novel and virtually unexplored therapeutic approach for HNSCC or other cancer types." (PMID 35120582, 2022). "In this study, TNBC cancer cells treatment with GW-8510 and two other CDK inhibitors all showed an increased level of cleaved caspase-3 and N-terminal fragments of GSDME, which is an indication of GSDME-mediated pyroptosis." (PMID 35756622, 2022). "Hence, GSDME may play different roles in different types of cancer." (PMID 34925465, 2021). "These functions and mechanisms recently had been reported to relate with cancer therapy, especially the GSDMD and GSDME." (PMID 34421915, 2021). "Additionally, 2‐bromopalmitate (2‐BP), which could inhibit the palmitoylation of C‐terminal domain GSDME and increase the interaction between C‐ and N‐ terminal domain of GSDME, counteracts chemotherapy drugs‐induced GSDME‐mediated pyroptosis in the cancer cells." (PMID 34590363, 2021). "Both gasdermin E (GSDME) and GSDMD, important pyroptosis substrates, are also emerging targets as prognostic biomarkers for the management of various cancers." (PMID 32703253, 2020). "GSDMA, GSDMB, GSDMC, GSDMD, GSDME (DFNA5), and DFNB59 constitute the gasdermin family and mediate pyroptosis in various types of cancer cells." (PMID 33348858, 2020). "Intriguingly, a recent study showed that necrosis/pyroptosis mediated by Gasdermin E/DNFA5, a caspase substrate, is induced by exposure of human and mouse cancer cells to chemotherapy; however, healthy mouse tissues were also affected by chemotherapy." (PMID 28945745, 2017). "Interestingly, certain GSDMs, such as GSDME, and to some extent GSDMA, are epigenetically silenced by DNA methylation in cancer cells, a repression that can be reversed with DNA methyltransferase inhibitors." (PMID 40783818, 2025). "Unlike most cancers where GSDME is epigenetically silenced, HCC shows a strikingly different pattern with significant GSDME overexpression." (PMID 40568597, 2025). "In the context of NSCLC, overexpression of GSDME leads to mitochondrial damage and activates the cGAS-STING-IFNβ signaling pathway, which promotes CD8+ T cell proliferation and results in favorable anti-cancer effects." (PMID 41291696, 2025). "Gasdermin E (GSDME), the most widely studied gasdermin in addition to GSDMD, can be cleaved by caspase-3 and transform TNF- or chemotherapy-induced apoptosis to pyroptosis, offering new insights into cancer treatment and antitumor immunity." (PMID 39349939, 2024). "Gasdermin E (GSDME) is a tumor suppressor gene and is inhibited in most cancers." (PMID 39526199, 2024). "Therefore, the GSDME-EGFR interaction plays an important role in NSCLC development, reveal a previously unrecognized link between GSDME and EGFR stability and offer new insight into cancer pathogenesis." (PMID 37085908, 2023). "The pore-forming proteins GSDMD and GSDME, extensively studied in the GSDM family, are potential targets for combating drug resistance and contributing to the treatment and prognosis of various cancers." (PMID 38239395, 2023). "This GSDME-dependent pyroptosis, a novel nonapoptotic mechanism of eliminating cancer cells, is downstream of the activated mitochondria-mediated caspase pathway." (PMID 36920176, 2023).
cancer (continued). "The expression level of C-myc and mitochondrial hexokinase II was suppressed in cancer cells treated with triptolide, which would accelerate mitochondrial translocation of BAD/BAX, leading to caspase-3 activation, GSDME cleavage, IL-1β, and LDH1 release, and pyroptosis ultimately." (PMID 38016064, 2023). "Additionally, the GSDME and GSDMB are cleaved directly by granzyme in cancer cells also, in turn, enhancing anticancer immunity." (PMID 36119049, 2022). "Cordyceps militaris extract, which is hydrosoluble fraction of dietary herb for cancer patients, is validated to induce PCD in A549 cell line through concomitantly activating caspase‐3‐dependent caspase‐3/PARP apoptosis and caspase‐3/GSDME pyroptotic pathways in vitro." (PMID 35035907, 2022). "Reportedly, GSDME-mediated pyroptosis supported the development of colorectal cancer (CRC) via the discharge of HMGB1, which promoted proliferating cell nuclear antigen (PCNA) expression and cancer cell proliferation." (PMID 36387211, 2022). "In different cancers, GSDMD and GSDME have different expression levels and functions." (PMID 36091247, 2022). "Synchronously, DCT up-regulates the expression of gasdermin E (GSDME, the specific pyroptosis-inducing substrate cleaved by caspase-3) by inhibiting DNA methylation, which leads to the cleavage of caspase-3 and enhanced cancer cell pyroptosis." (PMID 34596000, 2021). "Since cancer cells do not express GSDME, caspase-3 activation induces cancer cells to die in an apoptotic manner." (PMID 34484243, 2021). "It has been reported that natural killer (NK) cells and cytotoxic T lymphocytes could kill cancer cells by releasing granzyme A (GZMA) to cleave GSDMB and granzyme B (GZMB) to directly cleave GSDME to activate pyroptosis in cancer cells." (PMID 34616734, 2021). "Gasdermin family proteins, which include GSDMA, GSDMB, GSDMC, GSDMD, and GSDME, had been studied in other fields but not in cancers." (PMID 34298833, 2021). "It was confirmed that induction of CHOP regulated the BCL-2 family to trigger caspase-3/GSDME dependent pyroptosis as well as depression of glycolysis by restraint of the AKT–GSK3β–IGFBP1 axis, suggesting a potential role of CBD in modulating cancer cell PCD and metabolism." (PMID 34350183, 2021). "Due to epigenetic silencing mediated by DNA methylation, GSDME is not expressed in cancer cells but is highly expressed in many normal tissues." (PMID 34484243, 2021). "GSDME is frequently silenced in human cancers due to hyper-methylation of promoter DNA, making cancer cells lack of GSDME are resistant to pyroptosis." (PMID 34108030, 2021). "Due to immunity participation, GSDME-mediated anti-cancer pathways involve systemic responses and does not kill tumors alone." (PMID 34335940, 2021). "Chemotherapeutic reagents, such as etoposide, topotecan, CPT-11, and cisplatin, can induce pyroptosis in cancer cells via a GSDME-dependent mechanism, whereas they promote apoptosis in GSDME-negative cells." (PMID 34858408, 2021). "It worthy to note that either TPL or erastin alone exerted little effects on survival of C666–1 cells, but these two drugs synergistically killed the C666–1 cancer cell, implying TPL and erastin confer a synthetic vulnerability of GSDME-negative cancer cell." (PMID 34108030, 2021). "We first screened several cancer cell lines for the expression of GSDMD and GSDME." (PMID 32332857, 2020). "Gasdermin E (GSDME), also known as deafness autosomal dominant 5 (DFNA5) and previously identified to be an inducer of regulated cell death, is frequently epigenetically inactivated in different cancer types, suggesting that GSDME is a tumor suppressor gene." (PMID 31434357, 2019). "In addition, the biological characteristics of gasdermin D (GSDMD) and gasdermin E (GSDME), two important pyroptosis substrates, and their prognostic role in cancer management were reviewed." (PMID 31616642, 2019).
cancer (continued). "Notably, GSDME exerts its oncogenic role in HCC through pyroptosis-independent mechanisms, representing a paradigm shift in our understanding of gasdermin family proteins in cancer biology." (PMID 40568597, 2025). "Furthermore, the relationship between GSDME and IL2RG across various cancers was corroborated by the TIMER2 database, hinting at a potential indirect mechanism in which IL2RG activation may enhance GSDME-mediated pyroptosis." (PMID 40830889, 2025). "Alterations in mitochondrial metabolism and GSDME-driven pyroptosis may be relevant molecular signaling routes through which the delivery of mtDNA as DAMP may operate and exacerbate inflammation, which characterizes this type of cancer." (PMID 38732000, 2024). "Importantly, we demonstrated that the ectopic expression of PLK2, independent of its kinase activity, in several types of cancer cells promoted the caspase-3 processing, GSDME cleavage, DAMPs release, and cell death, albeit without IL-1β secretion." (PMID 38799433, 2024). "GSDME is always highly expressed in normal tissues, but the expression level is distinct among different cancers and episodically absent expression in some cancer, and the absent expression may be due to the methylation of the GSDME gene promoter." (PMID 39062587, 2024). "However, due to the hypermethylation of the promoter, the critical protein Gasdermin E (GSDME) is lacking in the majority of cancer cells, which cannot start the pyroptosis process and leads to dissatisfactory therapeutic effects." (PMID 38643134, 2024). "The Granzyme-B/GSDME and Granzyme-A/GSDMB driven pyroptosis have also been discovered in natural killer cells and lymphocytes, which may further enhance the immune response to cancer." (PMID 39398428, 2024). "When cleaved by CASP3, GSDME can switch noninflammatory apoptosis to pyroptosis in cancer cells." (PMID 37134086, 2023). "Additionally, some studies have found no discernible differences in GSDME expression between cancer and normal tissues." (PMID 38066523, 2023). "GSDME is not expressed in most cancer cells, but is expressed in a variety of normal tissues." (PMID 37542066, 2023). "Similarly, other chemotherapeutics, such as lobaplatin, doxorubicin, and paclitaxel, can induce cancer cells to undergo pyroptosis, rather than necroptosis, by activating caspase-3 to cleave GSDME in colorectal and lung cancer." (PMID 38066523, 2023). "Moreover, in contrast to previous observations that GSDME expression was negative or low within other cancer cells, GSDME protein levels were examined by Western blot analysis in several NSCLC cell lines, including A549, Calu-1, H1299, H1792 and H157 cells." (PMID 37085908, 2023). "Importantly, we showed that ectopic expression of PLK2 in several types of cancer cells promoted processing of Caspase-3, cleavage of GSDME, DAMPs release, and cell death, but not IL-1β secretion." (PMID 36646704, 2023). "In this review, we emphasize the PCD mediated by GSDME, summarize the key roles of GSDME in both cancer and non-cancer diseases, and describe the potential therapeutic approaches targeting GSDME, so as to provide directions for the targeted therapy in the future." (PMID 35462927, 2022). "It has been reported that the expression of GSDME in most cancer tissues is low or even absent." (PMID 34553845, 2022). "GSDME is absent in several types of cancer (e.g., colorectal cancer) due to promoter methylation." (PMID 34522213, 2021). "Despite accumulating cell- or animal-based experiments providing the relationship between Gasdermin E (GSDME) and human diseases, especially in malignant cancers, no pan-cancer analysis about the function of GSMDE in cancer management can be available up to date." (PMID 34381728, 2021). "But, the detail of how GSDME mediates cancer therapy has not been completely revealed and whether GSDME cleavage boosts cancer treatment in vivo has not been ultimately confirmed." (PMID 34335940, 2021).
cancer (continued). "Altogether, our results revealed that triclabendazole induces GSDME-dependent pyroptosis by caspase-3 activation at least partly through augmenting the ROS/JNK/Bax-mitochondrial apoptotic pathway, providing insights into this on-the-market drug in its potential new application in cancer treatment." (PMID 34305590, 2021). "Furthermore, our bioinformatic analysis of caspase -4, -9, and GSDME are well-established as cancer markers that are also involving in non-canonical pyroptotic mechanisms." (PMID 34659633, 2021). "Many cancer cells do not express GSDME due to its promoter methylation." (PMID 32332857, 2020). "Although the pro-tumorigenic and anti-tumorigenic effects of pyroptosis have been reported in various types of cancers, gasdermin E (GSDME)-mediated pyroptosis might result in normal tissue toxicity after chemotherapy." (PMID 32156008, 2020). "Additionally, GSDME-dependent pyroptosis can be triggered by intrinsic mitochondrial apoptosis and is a downstream event of the mitochondria-mediated caspase pathway, which is a non-apoptotic mechanism for eliminating cancer cells." (PMID 38044396, 2024). "However, a major challenge arises because most cancer cells do not express the necessary GSDME protein for caspase-3-driven pyroptosis, as the DFNA5 gene is often hypermethylated." (PMID 41291696, 2025).
infection (44 papers, 2017 to 2026). The state of being infected such as from the introduction of a foreign agent such as serum, vaccine, antigenic substance or organism. "Lung infectious viral burden (pfu/lung) was significantly reduced in GSDME-deficient mice at days 3 and 5 post-infection." (PMID 40481027, 2025). "GSDME has also been implicated in pathogen infections, and it was shown to initiate a lethal cytokine storm in H7N9 avian influenza viral infection." (PMID 38195694, 2024). "In contrast, infection of airway epithelial cells with the highly pathogenic IAV strain H7N9 triggered Gasdermin E (GSDME)-dependent pyroptosis, though the upstream mechanism is unclear." (PMID 36695550, 2023). "Mice deficient in GSDME survive the lethal infection of the highly pathogenic H7N9 virus." (PMID 39811662, 2025). "However, the role of GSDME-mediated pyroptosis in host response to pathogenic infections in chicken and the underlying mechanism remains to be elucidated." (PMID 39576037, 2025). "In line with this, GSDME deficient cells displayed reduced lytic cell death during infection." (PMID 38932190, 2024). "Tissue distribution results showed that GSDME and IL-1β transcription in the bursa of Fabricius and kidneys were significantly upregulated by more than five-fold (p < 0.01) following vvIBDV infection, indicating a close association with vvIBDV-induced tissue lesions." (PMID 42076745, 2026). "The percentage of cells that were positive for cleaved GSDME significantly increased at day 3 post-infection, correlating with a > 8-fold increase in GSDME+ cell counts." (PMID 40481027, 2025). "Cleaved caspase-3 is now known to lead to GSDME-mediated pyroptosis during infection with picornaviruses EV71, foot and mouth disease virus (FMDV) or EMCV." (PMID 39928567, 2025). "Our study revealed that PDCoV infection can trigger GSDME-mediated pyroptosis through the activation of caspase-3, a mechanism also observed in infections with many other viruses, such as SARS-CoV-2, HCoV-229E, ZIKV, IAV, and EV71 (35, –, 37, 39, –, 41)." (PMID 40503916, 2025). "Together, these data indicate that GSDME is dispensable for mounting a general antiviral and inflammatory response during acute infection." (PMID 40766393, 2025). "Here, confocal imaging of lung tissue sections from IAV-infected mice revealed cleaved GSDME in E-cadherin+ epithelial cells lining the bronchioles and alveoli at day 3 post-infection." (PMID 40481027, 2025). "A combination of flow cytometry, live-cell imaging and immunodetection of cleaved cell death proteins identified an increase in caspase-3 activation and GSDME cleavage in WT EMCV-infected cells compared to infection with 2B*KO EMCV." (PMID 39928567, 2025). "Suppression of GSDMD and/or GSDME expression was confirmed at 24 h following infection via immunoblot." (PMID 40481027, 2025). "We also show that despite this temporal difference in activation, suppression of both GSDMD and GSDME is required to significantly dampen both cell lysis and inflammation following Brazil/78 infection, suggesting possible redundancy." (PMID 40481027, 2025). "Our findings showed that GSDMD cleavage occurs after stimulation with LPS + Ng, whereas GSDME is cleaved after infection with VSV in human and mouse cells." (PMID 41550948, 2025). "Strikingly, silencing of GSDME in human bronchial epithelial cells limited infectious virus release following HKx31 and Brazil/78 infection." (PMID 40481027, 2025). "In A549 cells infected with VSV, elevated cytosolic mtRNA (ND5, ND6, and CYTB) indicated that GSDME cleavage by VSV infection contributes to mitochondrial membrane disruption." (PMID 41550948, 2025). "Together, these results demonstrate that neutrophil-specific GSDME deletion suppresses host inflammatory responses during infection and inflammation." (PMID 38195694, 2024). "Recent studies have identified GSDME as an executor of lytic cell death in the context of infection with different RNA virus." (PMID 38932190, 2024).